SMN1 (survival of motor neuron 1, telomeric)
Diseases named in the same sentence as SMN1 in open-access papers (continued):
Sharing a sentence is not in itself a finding about the gene and the disease.
spinal muscular atrophy (continued). "Spinal muscular atrophy (SMA), a leading genetic cause of infant death worldwide, is an autosomal recessive disorder caused by the loss of SMN1 (survival motor neuron 1), which encodes the protein SMN." (PMID 25514431, 2014). "The Spinal Muscular Atrophies (SMA) is a phenotypically diverse but genetically very similar group, in that the diseases are all caused by homozygous loss of the SMN1 gene." (PMID 24892836, 2014). "Spinal muscular atrophy (SMA), the most common autosomal recessive cause of infant death, is typically diagnosed by determination of SMN1 copy number." (PMID 24498607, 2013). "Two almost identical SMN genes are present on chromosome 5q13: the telomeric or SMN1 gene, which is the spinal muscular atrophy- determining gene, and the centromeric or SMN2 gene." (PMID 22047105, 2011). "Spinal muscular atrophy (SMA type I, II and III) is an autosomal recessive neuromuscular disorder caused by mutations in the survival motor neuron gene (SMN1)." (PMID 21762474, 2011). "Another example is spinal muscular atrophy (SMA), a neuromuscular disorder caused by mutations in the SMN1 gene that result in the degeneration of selected motorneurons." (PMID 24956164, 2011). "Spinal Muscular Atrophy (SMA), a severe autosomal recessive genetic disease in infants characterized by motor impairment and premature lethality, caused by mutations or loss of SMN1 and retention of SMN2." (PMID 22022549, 2011). "SMN1 is the determining gene for Spinal Muscular Atrophy (SMA), a devastating neurodegenerative disease in humans with no currently available FDA-approved drug treatment." (PMID 18791638, 2008). "Spinal Muscular Atrophy (SMA), a neurodegenerative disorder, is caused by the homozygous loss of survival motor neuron 1 (SMN1) and is the leading genetic cause of infantile death." (PMID 18941511, 2008). "Notably, AAV-based therapies, such as Luxturna (using AAV2 for RPE65 mutations causing Leber congenital amaurosis) and Zolgensma (using AAV9 for spinal muscular atrophy by replacing the SMN1 gene), have shown remarkable therapeutic outcomes." (PMID 41235102, 2025). "Chelex could also be implemented for spinal muscular atrophy screening, where they target the SMN1 gene from DBSs using qPCR." (PMID 40126229, 2025). "Copy number variants in the SMN1/SMN2 locus, which cause spinal muscular atrophy, may also lead to first trimester miscarriages as found in our study (PL-098D), however further investigation is required to establish this novel gene-disease association." (PMID 41256177, 2025). "Furthermore, in neonatal screening for spinal muscular atrophy, the SMN1 gene is analyzed from DBS samples." (PMID 40126229, 2025). "Spinal muscular atrophy (SMA) is a rare autosomal recessive neuromuscular disorder caused by homozygous absence of the survival motor neuron 1 (SMN1) gene." (PMID 40291843, 2025). "Their potential has been demonstrated by the United States Food and Drug Administration’s (FDA) approval of risdiplam for the treatment of spinal muscular atrophy (SMA), where it promotes the inclusion of exon 7 in SMN2, whose product then compensates for SMN1-inactivating mutations." (PMID 38609352, 2024). "Spinal muscular atrophy (SMA) is a recessively inherited neuromuscular condition caused by mutations in the survival motoneuron gene (SMN1), resulting in the absence of survival motor neuron protein (SMN)." (PMID 39201450, 2024). "Spinal muscular atrophy (SMA) is an inherited neuromuscular disease, and the majority of cases of SMA are caused by insufficient SMN protein levels due to the loss of function of the survival of the motor neuron 1 (SMN1) gene." (PMID 38334681, 2024). "Spinal muscular atrophy (SMA) is a severe neuromuscular disorder characterized by lower motoneuron degeneration and caused by reduced expression of the survival motor neuron (SMN) protein due to mutations or deletions in the SMN1 gene." (PMID 39246602, 2024).
spinal muscular atrophy (continued). "Spinal Muscular Atrophy (SMA): One of the most successful applications of RNA therapeutics in rare genetic diseases is the treatment of spinal muscular atrophy (SMA), a neurodegenerative disorder caused by mutations in the SMN1 gene." (PMID 39598489, 2024). "Spinal muscular atrophy (SMA) is a rare neuromuscular disease characterized by autosomal recessive inheritance and caused by biallelic loss of the survival motor neuron 1 (SMN1) gene, which primarily affects motor neurons in the anterior medullar horn and brainstem, leading to their apoptosis." (PMID 39060931, 2024). "Spinal muscular atrophy (SMA) is a rare genetic disorder characterized by weakness and atrophy of skeletal muscles caused by deletions or mutations in the survival motor neuron 1 (SMN1) gene and the presence of SMN2." (PMID 39432490, 2024). "Spinal muscular atrophy (SMA) is an autosomal recessive neurodegenerative disorder caused by deletions or variants in the survival motor neuron 1 (SMN1) gene, and approximately 95% of all patients with this condition have a homozygous SMN1 deletion." (PMID 37907848, 2023). "Spinal muscular atrophy (SMA) is an autosomal recessive disease resulting from homozygous mutations in the Survival Motorneuron 1 (SMN1) gene and the consequent production of a non-functioning SMN protein." (PMID 36902435, 2023). "Spinal muscular atrophy (SMA) is an autosomal recessive neuromuscular disorder caused, in approximately 95% of patients, by homozygous deletion of the survival motor neuron 1 gene (SMN1)." (PMID 36099045, 2022). "The promise of AAV9 serotype carrying human SMN1 in improving survival and motor functions of wheelchair-bound children with spinal muscular atrophy (SMA) spurred translation of several explorative research to clinical trials for neurodegenerative diseases with AAVs." (PMID 35663795, 2022). "The condition known as 5q spinal muscular atrophy (SMA) is a devastating autosomal recessive neuromuscular disease caused by a deficiency of the ubiquitous protein survival of motor neuron (SMN), which is encoded by the SMN1 and SMN2 genes." (PMID 35741415, 2022). "Spinal muscular atrophy (SMA) is an autosomal recessive disorder characterized by degeneration of lower motor neurons and progressive atrophy of skeletal muscles caused by variants in the survival motor neuron 1 (SMN1) gene." (PMID 33587247, 2021). "Spinal muscular atrophy (SMA), one of the leading inherited causes of child mortality, is a rare neuromuscular disease arising from loss-of-function mutations of the survival motor neuron 1 (SMN1) gene, which encodes the SMN protein." (PMID 34445667, 2021). "Spinal muscular atrophy (SMA), the leading genetic cause of infant mortality when untreated, is a motor neuron disorder caused by deletions or mutations of the survival motor neuron 1 (SMN1) gene." (PMID 34360794, 2021). "Spinal muscular atrophy (SMA) is a hereditary disease characterized by progressive muscle weakness and atrophy due to the degeneration of motor neurons caused by mutations in the SMN1 gene." (PMID 33512541, 2021). "Spinal muscular atrophy (SMA) is a heritable, autosomal recessive neuromuscular disorder, which encompasses a broader group of disease subtypes all sharing loss-of-function mutations/conversion or deletion in the survival of motor neurons 1 (SMN1) gene." (PMID 33999256, 2021). "This subsequently enhances the inclusion of exon 7 in the mRNA, and encodes a functional full-length protein, which is normally lacking in spinal muscular atrophy due to homozygous mutations or deletions of the SMN1 gene." (PMID 32481522, 2020). "Spinal muscular atrophy (SMA), the leading genetic cause of infant mortality, is characterized by the specific degeneration of spinal motor neurons caused by the mutation in the SMN1 gene." (PMID 30910806, 2019).
spinal muscular atrophy (continued). "5q-associated spinal muscular atrophy (SMA) is one of the most common neuromuscular diseases in childhood and is caused by homozygous deletion or less frequently other mutations in the survival motor neuron 1 gene (SMN1)." (PMID 31736847, 2019). "Also, the Food and Drug Administration (FDA) has approved an antisense oligonucleotide directed against mutant survival motor neuron gene 1 (SMN1) for treatment of spinal muscular atrophy, characterized by alteration of lower motor neurons." (PMID 31572186, 2019). "MLPA of SMN1/2 in the proband excluded spinal muscular atrophy." (PMID 30770808, 2019). "Spinal muscular atrophy (SMA) is an autosomal recessive neuromuscular disorder characterized by atrophy and weakness of skeletal muscles caused by mutations of the survival motor neuron 1 gene (SMN1)." (PMID 31671515, 2019). "Spinal Muscular Atrophy (SMA) is a severe autosomal recessive disease characterized by selective motor neuron degeneration, caused by disruptions of the Survival of Motor Neuron 1 (Smn1) gene." (PMID 29902268, 2018). "In consequence, splicing defects on SMN1 and SMN2—and the emergence of a neurodegenerative disorder such as spinal muscular atrophy—might be associated with a subset of hnRNP proteins." (PMID 30487551, 2018). "This review incorporates an overview of the clinical manifestations, genetics, and pathophysiology of inherited paediatric motor neuron disorders beyond classic SMN1-related spinal muscular atrophy and describes recent advances in next generation sequencing and its clinical application." (PMID 28634552, 2017). "Proximal spinal muscular atrophy (SMA) is a neuromuscular disorder caused by the degeneration of alpha motor neurons and is characterized by a mutation in the survival motor neuron gene (SMN1); however, all patients retain a nearly identical copy of SMN2." (PMID 29104258, 2017). "Spinal muscular atrophy (SMA) is an autosomal recessive disorder; in almost 95 % of all cases, there is a homozygous deletion or mutation of the Survival Motor Neuron 1 gene (SMN1)." (PMID 26499462, 2015). "Direct in vivo gene therapy has been used in Spinal Muscular Atrophy (SMA) treatment, where the SMN1 gene is delivered using an AAV9 vector, targeting motor neurons directly." (PMID 41235102, 2025). "Proximal spinal muscular atrophy (SMA), the most frequent genetic cause of infant death prior to the development of disease-modifying treatments, is caused by autosomal recessive deletions or mutations in the ubiquitously expressed survival motor neuron 1 (SMN1) gene." (PMID 39690843, 2025). "Spinal muscular atrophy (SMA), a neuromuscular disease, is the second most common recessive disorder and caused by pathogenic variants affecting the Survival of Motor Neuron (SMN1) gene (localized on the long arm of chromosome 5; 5q-related SMA) subsequently leading to reduced protein abundances." (PMID 38470509, 2024). "5q-associated spinal muscular atrophy (SMA) is an autosomal-recessive motor neuron disorder, clinically characterized by muscle weakness and atrophy caused by degeneration of alpha motor neurons due to a homozygous deletion or mutation in the survival motor neuron 1 (SMN1) gene." (PMID 39206217, 2024). "Spinal muscular atrophy (SMA) is an orphan hereditary disease characterized by skeletal muscle weakness and atrophy due to decreased transcriptional levels of survival motor neuron (SMN) protein caused by mutation or deletion of the survival motor neuron 1 (SMN1) gene." (PMID 37936690, 2023). "Of these five drugs, tafenoquine succinate (a FDA-approved antimalarial drug targeting CYC1) and branaplam (a Phase 3 clinical trial drug targeting SMN1 for the treatment of spinal muscular atrophy) have not been reported as being associated with hepatocellular carcinoma." (PMID 37594310, 2023).
spinal muscular atrophy (continued). "Spinal muscular atrophy (SMA), caused by a deficiency of the survival motor neuron‐1 (SMN‐1) protein, is a severe neuromuscular disorder characterised by muscle atrophy and loss of motor function; interestingly, SMN‐1‐deficient myoblasts display reduced motility." (PMID 33210465, 2020). "In children, the most common inherited motor neuron disease is spinal muscular atrophy (SMA) due to homozygous disruption of the survival motor neuron 1 (SMN1) gene, with classic phenotypes prompting targeted SMN1 gene testing." (PMID 28634552, 2017). "Newborn screening (NBS) for spinal muscular atrophy (SMA) enables rapid diagnosis and pre-symptomatic treatment of infants with bi-allelic SMN1 deletions." (PMID 41687605, 2026). "We recruited 17 subjects with type II or type IIIa spinal muscular atrophy (SMA)and obtained the SMN1 and SMN2 copy numbers in 16 of them." (PMID 38230872, 2024). "(ii) Zolgensma (onasemnogene abeparvovec), developed by Novartis and approved in 2019 for the treatment of spinal muscular atrophy (SMA) in pediatric patients under 2 years of age, using AAV9 vector to deliver functional SMN1 gene to motor neurons." (PMID 39194716, 2024). "ASOs designed to correct the SMN1 gene and restore the SMN protein have been reported to improve muscle function in spinal muscular atrophy patients." (PMID 39272802, 2024). "However, it is possible that change could be facilitated by the addition of IKD and LIKD to the RUSP as core conditions and with emphasis on the nominated screening strategy following the precedent of screening for spinal muscular atrophy by only testing for deletion of exon 7 in SMN1." (PMID 38390974, 2024). "In a recent study, the MS assay was also applied in CNV detection of SMN1 and SMN2 genes for spinal muscular atrophy genetic testing, showing highly concordant results with MLPA." (PMID 38274092, 2023). "The approved gene therapies for spinal muscular atrophy (SMA), caused by loss of survival motor neuron 1 (SMN1), greatly ameliorate SMA natural history but are not curative." (PMID 36849544, 2023). "Spinal muscular atrophy (SMA) is a common devastating neuromuscular disorder, usually involving homozygous deletion of the SMN1 gene." (PMID 36421785, 2022). "Recently, a rAAV9 vector carrying SMN1 (rAAV9.SMN1, Zolgensma) was FDA-approved as gene therapy to treat spinal muscular atrophy." (PMID 36258013, 2022). "Most children with biallelic SMN1 deletions and three SMN2 copies develop spinal muscular atrophy (SMA) type 2." (PMID 35715567, 2022). "Since the approval of modifying therapies for Spinal Muscular Atrophy (SMA), several protocols aiming to screen SMN1 homozygous deletion in a neonatal context have been published." (PMID 34449526, 2021). "In the next five years, many NBS programs will have implemented a multiplex PCR, measuring TRECs simultaneously with KRECs and SMN1 introducing NBS for XLA and spinal muscular atrophy (SMA)." (PMID 34842618, 2021). "Indeed, NBS for spinal muscular atrophy is nowadays largely accepted amongst pediatricians, families and advocacy groups, although screening assays specifically focus only on the identification of homozygotic deletions of the SMN1 gene and miss SMN1 heterozygotic and SMN2 deletions." (PMID 33542429, 2021). "Other notable genes include SMN1 (94.6% dark CDS) and SMN2 (88.0% dark CDS), which are known to be involved in spinal muscular atrophy (SMA) and ALS." (PMID 31104630, 2019). "In people with the disease spinal muscular atrophy (SMA), both alleles of SMN1 are non-functional, but increased levels of SMNFL, usually resulting from SMN2 gene duplication, correlate with longer survival times." (PMID 28728573, 2017). "Homozygous deletion of SMN1 was shown to be accompanied by intron retention in the U12-type intron from the ATXN10 and Thoc2 genes in lymphoblasts derived from patients with spinal muscular atrophy." (PMID 23752268, 2013).
spinal muscular atrophy (continued). "Likewise, Zolgensma, a spinal muscular atrophy drug, is an AAV serotype 9 (capsid-type-9) that carries the survival motor neuron 1 (SMN1) gene to neurons via crossing the blood-brain barrier." (PMID 40072100, 2025). "Zolgensma, an FDA-approved treatment for patients < 2 years of age with spinal muscular atrophy, utilizes adenovirus vector 9 (AA9) for the delivery of the survival motor neuron 1 (SMN1) gene to motor neurons in the central nervous system for the production of the SMN protein." (PMID 40573436, 2025). "For example, homozygous absence of exon 7 in SMN1 is found in approximately 95% of patients with spinal muscular atrophy, the most common disease of genetic motor neuron disease." (PMID 38361118, 2024). "External testing solved 3 cases with a negative WES result (2 with spinal muscular atrophy (SMN1) and 1 with myotonic dystrophy type 2 (CNBP); NGS data of these cases were not re-analyzed)." (PMID 38127101, 2024). "Zolgensma is an AAV-9 based, one-time only gene therapy which supplements the survival of motor neuron 1 (SMN1) protein in patients with spinal muscular atrophy (SMA), which is functionally lacking in these patients." (PMID 38483631, 2024). "Spinal muscular atrophy (SMA) is an inherited neuromuscular disease marked by progressive muscle weakness and atrophy, and it is caused by the absence of the survival motor neuron 1 (SMN1) gene." (PMID 39585055, 2024). "Spinal muscular atrophy (SMA) is a neuromuscular disorder arising from biallelic non-functional survival motor neuron 1 (SMN1) genes with variable copies of partially functional SMN2 gene." (PMID 36911944, 2023). "The SMN1 gene and its product, the SMN protein, are potential therapeutic targets for spinal muscular atrophy, and the dysregulation of snRNAs may serve as a potential biomarker." (PMID 38003403, 2023). "In addition to the standard GATK pipeline, specific bioinformatics tools have been used to improve the deletion detection of SMN1 and HBA1/HBA2 in spinal muscular atrophy and thalassaemia, respectively." (PMID 35314707, 2022). "This leads to the production of full-length SMN protein from SMN2, which alleviates the spinal muscular atrophy symptoms due to lack of protein produced from SMN1." (PMID 34882671, 2021). "Two unrelated probands (one adult, one pediatric) had been clinically diagnosed with spinal muscular atrophy (with negative SMN1 testing) prior to undergoing additional genetic testing including TTN." (PMID 32815318, 2020). "Spinal muscular atrophy (SMA) as a prototype is an excellent example, where, the majority of SMA patients are homozygous for SMN1-exons 7-8 deletion; however, phenotype severity is directly influenced by SMN2 (SMN1 pseudogene) copies that determine SMA subtype and can ameliorate the SMA phenotype." (PMID 37628591, 2023). "The human genome is the only one that contains two SMN genes (SMN1 and SMN2), whereas all species used to model spinal muscular atrophy (SMA) have only one SMN gene equivalent to SMN1." (PMID 37894969, 2023). "Despite the lack of affected children with spinal muscular atrophy in our cohort, we identified an SMN1 carrier frequency of 1/54, which is in the higher range reported for different populations (1/100–1/50) and in line with the expectation for a mainly European cohort." (PMID 35906228, 2022). "For infants with three copies of SMN1 at risk for spinal muscular atrophy (SMA) type 1, onasemnogene abeparvovec improves ventilator-free survival and nutritional/respiratory independence and allows motor development indistinguishable from healthy children without SMA." (PMID 35715567, 2022). "Notably, we also did not report the Syrian Jewish carrier frequency for SMN1 (MIM#: 600354) for spinal muscular atrophy (SMA) even though it is the most common autosomal recessive disease across worldwide populations." (PMID 34288589, 2021).